PAX8 (paired box 8)
Diseases named in the same sentence as PAX8 in open-access papers (continued):
Sharing a sentence is not in itself a finding about the gene and the disease.
ovarian carcinoma (continued). "Moreover, PAX8 was found to be highly expressed in ovarian cancer and has exhibited pro‐proliferative effect." (PMID 33830648, 2021). "Lineage-restricted transcription factor PAX8 is oncogenic in ovarian cancer cells." (PMID 33903593, 2021). "Taken together, ADSCs may advance the proliferation of ovarian cancer cells through the PAX8 up‐regulation." (PMID 33830648, 2021). "Therefore, the results show that ADSCs can advance the ovarian cancer growth rate and metastasis, and silencing PAX8 expression can reverse this effect." (PMID 33830648, 2021). "However, the PAX8 protein is regarded to be a promising target for ovarian cancer treatment based on its pervasive expression in these cancer cells." (PMID 34540435, 2021). "Furthermore, the capability of ADSCs to promote tumour growth, metathesis and invasion was inhibited by silencing PAX8 in ovarian cancer cells both in vitro and in vivo." (PMID 33830648, 2021). "This gives PAX8 gene the advantage of being a prognostic factor of ovarian cancer as well." (PMID 34540435, 2021). "However, the PAX8 gene was found to play an essential role in the motility, adhesion, invasion, and tumorigenesis of ovarian cancer cells by modulating these cells' interaction with the extracellular matrix." (PMID 34540435, 2021). "Collectively, PAX8 might be associated with TAZ protein stability and could increase TAZ expression in ovarian cancer cell lines." (PMID 33830648, 2021). "Similarly, in ovarian cancer, systemic loss-of-function shRNA screen identified 50 essential and amplified genes including CCNE1, PAX8, FRS2, PRKCE, and RPTOR." (PMID 33669749, 2021). "Moreover, patients with ovarian cancer that have high PAX8 levels are more likely to relapse and usually show a poor clinical prognosis." (PMID 33830648, 2021). "Then, the effect of ADSCs on PAX8 level was studied in ovarian cancer cells." (PMID 33830648, 2021). "Our findings indicate that the PAX8 expression increment could contribute a role in promoting the ADSC‐induced ovarian cancer cell proliferation through TAZ stability regulation." (PMID 33830648, 2021). "In addition, the PAX8 expressions in 4 cell lines of ovarian cancer were detected by Western blot, and the results showed that SKOV3 cells expressed a higher level of PAX8 while A2780 cells expressed a relatively lower level." (PMID 33830648, 2021). "Moreover, Co‐IP assays in ovarian cancer cells revealed that an interaction existed between endogenous PAX8 and TAZ." (PMID 33830648, 2021). "We here report an additional role of PRDM3 in ovarian cancer as a PAX8 cofactor." (PMID 33903593, 2021). "Based on the immunohistochemical studies, the PAX8 gene was clearly expressed in the primary ovarian cancer cells but not in the metastatic ovarian cancer cells, which indicates the high specificity of this gene expression in primary ovarian cancer cells." (PMID 34540435, 2021). "In addition, Chai et al25 reported that higher PAX8 expressed patients with epithelial ovarian cancer exhibited shorter post‐operative survival times." (PMID 33830648, 2021). "Whereas, for the ovarian carcinomas, PAX-8 was under expressed." (PMID 32847623, 2020). "PAX8 was overexpressed in the majority of the ovarian cancer cell lines." (PMID 33488950, 2020). "This study aimed at investigating the immunohistochemical expression of PAX-8 among Sudanese females diagnosed with cervical, endometrial, and ovarian cancers between December 2017 and May 2019 by studying their Formalin-fixed paraffin embedded blocks." (PMID 32847623, 2020). "Since we have demonstrated that PAX8 is involved in cell migration and adhesion, we asked whether it could also affect anoikis resistance of ovarian cancer cells." (PMID 31832016, 2019). "However, both mechanistic underpinnings and pharmacological actionability of PAX8 as an ovarian cancer driver are by far elusive, precluding its clinical translation at the current stage." (PMID 31050342, 2019).
ovarian carcinoma (continued). "(C) Immunohistochemical staining of PAX8 in tissue microarrays containing 674 ovarian cancer cases." (PMID 31050342, 2019). "(A) PAX8 immunoblotting across a panel of ovarian cancer cell lines." (PMID 31050342, 2019). "(D) Confined gene expression of the PAX8 regulon in ovarian cancer cell lines." (PMID 31050342, 2019). "COPA identifies a lineage-specific PAX8 regulon in ovarian cancer." (PMID 31050342, 2019). "PAX8 is a prototype lineage-survival oncogene in epithelial ovarian cancer." (PMID 31050342, 2019). "Having identified the HDAC-mediated epigenetic regulation of lineage-dependent PAX8 in ovarian cancer, we became aware that an analogous concept might be broadly applicable to other tumor types." (PMID 31050342, 2019). "To analyze the PAX8-Integrin β3 network that could govern migration and adhesion in ovarian carcinoma, we re-analyzed our previous RNA-seq data using the Cytoscape platform." (PMID 31832016, 2019). "Interestingly, inhibition of PAX8 gene expression in ovarian cancer cells decreases tumor cell adhesion to fibronectin and collagen." (PMID 31832016, 2019). "On the basis of these data, we proposed that chemotherapy combined with HDAC inhibitors might represent a valuable therapeutic option to produce robust and durable benefit for ovarian cancer patients featured by PAX8 dependency." (PMID 31050342, 2019). "Similarly, tumors resembling high-grade serous ovarian cancer (HGSOC) are observed when prototypical ovarian cancer lesions are induced in PAX8-expressing FTSEC39." (PMID 31431624, 2019). "PAX8 expression was absolutely required for predicting ovarian cancer (OR ≥ 999.99, P < 0.001)." (PMID 30024911, 2018). "PAX8 expression in peritoneal fluid samples was necessary for the prediction of ovarian cancer." (PMID 30024911, 2018). "In this review, we examine the implications of PAX2 and PAX8 expression in the cell of origin of serous cancer and their potential efficacy as drug targets by summarizing their role in the molecular pathogenesis of ovarian cancer." (PMID 30096791, 2018). "Samples from ovarian cancer patients were large 3D cluster/CK7+/PAX8+ with AUC of 0.9812." (PMID 30024911, 2018). "However, in ovarian cancer, knockdown of PAX8 was found to reduce cancer cell proliferation, migration, and invasion." (PMID 30021604, 2018). "Analysis of The Cancer Genome Atlas (TCGA) data indicates that PAX8 mRNA expression is significantly upregulated in high-grade serous ovarian cancers (HGSOC) compared to normal fallopian tube tissues (p = 0.007); but the role of PAX8 in other ovarian cancer histotypes is poorly understood." (PMID 29312534, 2017). "For example, WNT7A known to function as tumor-promoting in ovarian cancer is present at very low level in FT194 cells but becomes highly expressed in SKOV-3 cells where is significantly downregulated upon PAX8 silencing." (PMID 27259239, 2016). "In addition, the Cancer Genome Atlas (TGCA) Project indicated PAX8 as a survival gene essential for the proliferation of ovarian cancer cells." (PMID 27259239, 2016). "Assessment of representative sections from the entire fallopian ducts of 11 patients with high risk of developing ovarian cancer revealed presence of cytoplasmic/nuclear βcatenin, LEF1, Pax8 and Stathmin 1-positive precursor lesions in all of the patients (SFigure 1)." (PMID 27588493, 2016). "All together, our results show that the expression profiles affected by PAX8 silencing might reflect an ongoing transformation process reinforcing the involvement of this transcription factor in ovarian cancer." (PMID 27259239, 2016). "The pathways that PAX8 may regulate in ovarian cancer and in Fallopian tube secretory cells are still undefined." (PMID 27259239, 2016).
ovarian carcinoma (continued). "We believe that our analysis has led to the identification of candidate genes and pathways regulated by PAX8 that could be additional targets for the therapy of ovarian carcinoma." (PMID 27259239, 2016). "However, its function in Fallopian tube secretory epithelial cells, as well as the entire molecular network that allows PAX8 to regulate cellular processes in these cells and in ovarian cancer cells, is still an unexplored field." (PMID 27259239, 2016). "Here, we hypothesize that one way in which PAX8 confers a proliferative advantage to ovarian cancer cells is through the regulation of procancer factors, like FGF18, in a pathological microenvironment." (PMID 27259239, 2016). "In this study, to uncover genes and pathways downstream of PAX8 involved in ovarian carcinoma we have determined the molecular profiles of ovarian cancer cells and in parallel of Fallopian tube epithelial cells by means of a silencing approach followed by an RNA-seq analysis." (PMID 27259239, 2016). "Interestingly, our RNA-seq analysis identifies, among PAX8 potential targets, genes that have been reported in the literature having a role in ovarian cancer." (PMID 27259239, 2016). "Furthermore, immunocytochemical analysis demonstrated strong expressions of ovarian epithelial cancer cell and mesothelial cell markers, PAX8 and calretinin, in both types of OCSPC, implicating that a mesothelial origin of the OCSPCs was most likely." (PMID 26597084, 2015). "It has been recently reported that PAX8 is expressed in a subset of epithelial tumors and could be a useful marker for the detection and differential diagnosis of ovarian carcinoma." (PMID 24766781, 2014). "To examine whether high levels of PAX8 could directly contribute to the tumorigenicity of ovarian cancer cells, we analyzed whether PAX8 silencing was able to modify the oncogenic properties of SKOV-3 cells." (PMID 24766781, 2014). "In this study, we investigated the contribution of PAX8 in ovarian cancer progression." (PMID 24766781, 2014). "Interestingly, aberrant expression of PAX8 has been reported in epithelial ovarian cancer, and it was described as one of the top 40 genes specifically upregulated in different types of ovarian carcinomas." (PMID 24766781, 2014). "Indeed, wound closure of the siCl48 clone (that expresses very low levels of PAX8) was not significant after 8 hours and was only partial after 24 hours, suggesting that PAX8 silencing strongly reduces the migration ability of SKOV-3 ovarian cancer cells." (PMID 24766781, 2014). "In 2003, analysis of the PAX8 gene by DNA microarray revealed high expression in ovarian cancer." (PMID 23425942, 2013). "All ascitic samples showing PAX8+/Calretinin- from patients who might receive NACT were 100% correlated to the final diagnosis of ovarian cancer." (PMID 23958394, 2013). "In addition, PAX8 has been reported to be useful for the detection and differential diagnosis of ovarian carcinoma." (PMID 23425942, 2013). "Therefore it is tempting to postulate that the requirement for PAX8 for the survival and proliferation of ovarian cancer cell lines represents exactly such a regulatory mechanism." (PMID 23528888, 2013). "In the present study, we evaluated if, in addition to the routine morphologic diagnosis, the biomarker PAX8 could be useful in recognition of ovarian epithelial cancer cells prior to the neoadjuvant chemotherapy." (PMID 23958394, 2013). "In tissues other than the thyroid, PAX8 was found overexpressed in epithelial ovarian cancer and it has been hypothesized that PAX8 maybe an important regulator of telomerase activity and cell survival in some gliomas." (PMID 21966443, 2011). "Moreover, PAX8 promotes proliferation and has an anti-apoptotic role in ovarian cancer cells." (PMID 40506992, 2025). "Knockdown of PAX8 could inhibit the proliferation, invasion and migration of ovarian cancer cells." (PMID 35548853, 2022).
ovarian carcinoma (continued). "Interestingly, a significant downregulation of the Integrin αvβ3 signal on the cell membrane was observed in good correlation with PAX8 inhibition indicating an important contribution of PAX8 for the presence of the αvβ3 heterodimer on the surface of ovarian cancer cells." (PMID 31832016, 2019). "In addition, PAX8 has been found to be expressed at high levels in ovarian carcinomas and serous effusions, indicating that PAX8 detection may prove useful in the clinic." (PMID 23425942, 2013). "The PAX8 and SOX17 complex in ovarian cancer cells promoted the secretion of angiogenic factors by suppressing the expression of SERPINE1, which encodes a proteinase inhibitor with anti-angiogenic effects." (PMID 40506992, 2025). "This includes FOXA1, IRF4, PAX8, and SOX10 which are respectively highly selectively essential in neuroblastoma, lymphoma, ovarian cancer, and glioma compared to all other cancer types." (PMID 39536500, 2024). "Genes that contributed to the most variation between subtypes included known biomarkers and master regulators of ovarian cancer subtypes (MUC16 and PAX8) and many keratin and cadherin genes (KRT19, KRT7, KRT8, CDH6, and CDH1)." (PMID 39131380, 2024). "Another study demonstrated that PAX8 and SOX17 facilitated the secretion of angiogenic factors by ovarian cancer cells." (PMID 37856473, 2023). "In sum, ADSCs increase the ovarian cancer cell proliferation at least partially by up‐regulating the PAX8 expression and by maintaining TAZ stability in ovarian cancer cells." (PMID 33830648, 2021). "Collectively, our data suggest that PAX8 is a major TF in ovarian cancer cells by engaging a large number of genomic sites, while PRDM3 (MECOM) is specifically recruited by PAX8 at specific genomic loci to modulate a defined common gene module." (PMID 33903593, 2021). "Combined, this study lays the foundation for studying PAX8 and MECOM as therapeutic targets for epithelial ovarian cancer." (PMID 33903593, 2021). "In addition, an overexpression of PAX8 could elevate the proliferation of ovarian cancer cells." (PMID 33830648, 2021). "(F) Regulatory network of the PAX8 regulon as inferred by individually knocking out each member with CRISPR-Cas9 system and quantifying relative gene expression in ovarian cancer cells." (PMID 31050342, 2019). "Other notable DMGs include key markers of ovarian cancer such as MUC16 (CA-125) and PAX8, as well as genes that play key roles in ovarian cancer biology such as CCNE1 and MTHFR." (PMID 31870409, 2019). "Several guidelines recommended GCDFP-15 and mammaglobin staining in cases of suspected breast cancer, while PAX-8 and WT-1 are recommended IHC markers for CUP with suspected ovarian cancer." (PMID 29433539, 2018). "The power to predict the primary site was best in ovarian cancer (AUC of 0.9812), which was specific to large 3D cluster/CK7+/PAX8+ for differentiating ovarian cancer from gastrointestinal tract cancers." (PMID 30024911, 2018). "WT1, PAX8, and GCDFP-15 play a major role in distinguishing between primary and metastatic breast cancers from ovarian cancer, and over 90% of ovarian serous carcinomas are WT1 positive." (PMID 27047697, 2016). "PAX8 is expressed at high levels in SKOV-3, TOV-21G and OVCAR-3 ovarian cancer cell lines, whereas it is undetectable in two primary normal ovarian cultures (medullary and cortical cells) and in the TOV-112D and A2780 ovarian cancer cell lines." (PMID 24766781, 2014).
ovarian carcinoma (continued). "We observed that the knock-out of these genes compared to PAX8 (an established tumorigenic factor in HGSOC) has no influence on tumour cell proliferation in 57 different epithelial ovarian cancer cell lines." (PMID 38361045, 2024). "Importantly, when genetic lesions frequently occurring in ovarian cancer are induced in PAX8+ FTSEC, tumors resembling HGSOCs occur, suggesting that PAX8 is expressed in the cells of origin of HGSOC." (PMID 33903593, 2021). "Quantification in the right panel indicated that PAX8 was expressed in various histotypes of ovarian carcinomas, but not adjacent or normal tissues." (PMID 31050342, 2019). "Specifically, PAX8 is frequently upregulated and functionally essential in a major subset of ovarian cancer, regardless of distinct somatic alterations or histologies." (PMID 31050342, 2019). "In contrast to ovarian cancer, gastric cancer shows little or no expression of PAX8, suggesting conflicting roles of PAX8 in cancer progression." (PMID 30021604, 2018). "In 2003, a gene expression study carried out in ovarian carcinoma reported the transcription factor PAX8, normally absent in ovarian surface epithelial cells, among the most highly expressed genes." (PMID 27259239, 2016). "Despite PAX8 is normally expressed in Fallopian tube secretory cells, namely the cell of origin of HGSC, and is mainly considered a marker of tumor origin, we have recently reported its pivotal function in the tumorigenic phenotype of ovarian cancer cells." (PMID 27259239, 2016). "For example, our data show that chordin (CHRD), a BMP extracellular regulator that behaves as suppressor of tumorigenesis in ovarian carcinoma cells, is abundantly expressed and regulated by PAX8 in FT194 cells, while is almost absent in SKOV-3 cells." (PMID 27259239, 2016). "In a study in malignant ascites, a hundred percent of primary ovarian cancers were positive in PAX8, while those of non-Müllerian origin were all negative." (PMID 27047697, 2016). "Furthermore, it has been reported previously that PAX8 is expressed in serous, endometrioid, and mucinous ovarian cancer while expression of WT1 is restricted to the serous subtype of ovarian cancer." (PMID 24603706, 2014). "By contrast, PAX8 was stained in none of the breast and almost all ovarian cancer samples, indicating that PAX8 is a more superior marker for the differential diagnosis of ovarian and breast cancer." (PMID 23425942, 2013). "Due to the fact that WT1 gene has been shown to be transcriptionally regulated by some upstream transcriptional factors like Sp1, PAX2, PAX8 and PEA3, it is worthwhile to further analyze the expression status of these upstream molecules in ovarian cancer specimens obtained from this population." (PMID 16606472, 2006). "Similarly, lipofuscin accumulation is detected in the stromal/Pax8 negative compartment of Carboplatin-treated ovarian cancer patients compared to untreated ones." (PMID 36552790, 2022). "As mentioned in the rules for breast cancer cell lines, PAX8 is highly expressed in ovarian cancer and could be a remarkable feature for discriminating between breast cancer and ovarian cancer." (PMID 34917619, 2021). "PAX8 occupies an intragenic enhancer in the LYPD1 gene locus for LYPD1-expressing ovarian cancer cell lines OVCAR3, KURAMOCHI, and COV318 but not OVCAR4, suggesting that PAX8 might contribute to the transcriptional regulation of LYPD1 expression." (PMID 34290299, 2021). "In addition, due to the enriched expression of PRDM3 in ovarian cancer cells, we validated that PRDM3 alone can interact with PAX8 by co-immunoprecipitation of ectopically expressed PAX8 and PRDM3 in HEK293 cells, as well as by complementation assay using a cellular NanoBit assay." (PMID 33903593, 2021).